IL19 (interleukin 19)
Diseases named in the same sentence as IL19 in open-access papers (continued):
Sharing a sentence is not in itself a finding about the gene and the disease.
breast carcinoma (continued). "Specially, IL19 has been proposed as a prognostic marker in breast cancer, and its expression is correlated to advanced tumor stage, metastasis, and poor survival." (PMID 26979459, 2016). "We recently reported that upregulated IL-19 in breast cancer promotes tumor progression and affects clinical outcome." (PMID 24130695, 2013). "It would be interesting to explore the relationship between HER2 expression and the hypoxia/IL-19/CXCR4 pathway in the progression of breast cancer." (PMID 23710200, 2013). "In breast cancer, IL-19 expression is correlated with increased mitotic figures, advanced tumor stage, higher metastasis, and poor survival." (PMID 23710200, 2013). "We conclude that IL-19 has an autocrine effect on breast cancer cells and provides a microenvironment for tumor progression." (PMID 23710200, 2013). "IL-19 treatment promotes specific proliferation and migration activities as well as fibronectin expression and assembly both in human and in mouse breast cancer cells." (PMID 23710200, 2013). "We previously reported that in breast cancer IL-19 induces fibronectin expression and assembly, which is associated with lung metastasis." (PMID 24130695, 2013). "We recently reported that upregulated IL-19 in breast cancer promoted tumor progression and affected clinical outcome: increased IL-19 expression in invasive ductal carcinoma (IDC), human breast tissue was associated with tumor staging." (PMID 23710200, 2013). "Accumulated clinical and experimental data indicate that IL-19 is an important mediator in breast cancer." (PMID 23710200, 2013). "TGFβ-1, VCAN, and IL19 are comparatively expressed more in Luminal subtype of breast cancer." (PMID 41348904, 2025). "IL-19 promotes breast cancer cell invasion and induces the phosphorylation of ERK, p38, and AKT." (PMID 40057744, 2025). "The expression pattern of TGFβ-1, IL19, CXCR4, BMP1, VCAN, and WNT2 in different molecular subclasses of Breast Cancer revealed that TGFβ-1, IL19, CXCR4, BMP1, VCAN, and WNT2 mRNA levels are higher in luminal A followed by luminal B, HER2 and Basal-like respectively." (PMID 41348904, 2025). "Additionally, it was found that IL-19 directly helps proliferate and migrate breast cancer and indirectly promotes the progression of the tumour by providing the required microenvironment." (PMID 35928364, 2022). "The stages of breast cancer caused clear differences in the levels of TNF-α and IL-19." (PMID 35928364, 2022). "The differences between TNF-α and IL-19 at different stages of breast cancer." (PMID 35928364, 2022). "A wide body of clinical and experimental works confirms that IL-19 is a key agent in breast cancer." (PMID 35928364, 2022). "In breast cancer, interleukin 19 seems to play an especially important role in disease progression." (PMID 34554372, 2021). "The IL-19 protein promotes proliferation and metastasis in breast cancer cells." (PMID 33330580, 2020). "The effect of IL-19 on FN expression and assembly in breast cancer cells has been investigated." (PMID 23710200, 2013). "IL-19 induces the expression of CXCR4 in breast cancer cells." (PMID 23710200, 2013). "Moreover, IL-19 overexpression promotes the proliferation, migration, tumor growth, and metastasis of breast cancer cells." (PMID 23710200, 2013). "It directly promotes proliferation and migration and indirectly provides a microenvironment for tumor progression, which suggests that IL-19 is a prognostic marker in breast cancer and that antagonizing IL-19 may have therapeutic potential." (PMID 23710200, 2013). "The mechanisms of IL-19 in breast cancer have recently been explored both in vitro and in vivo." (PMID 23710200, 2013). "Moreover, UALCAN was utilized to get the expression pattern of IL-19 in different subclasses and stages of breast cancer, and the results revealed that IL-19 is highly upregulated in the Luminal type of BC subtype, and the expression is upregulated in stage 3 of BC followed by stage 2." (PMID 37675062, 2023).
breast carcinoma (continued). "Additionally, it could be concluded from the obtained results that inhibiting IL-19 could be helpful in the treatment of breast cancer." (PMID 35928364, 2022). "We also found that the expression level of IL20RA ligands IL-19, IL-20, and IL-24 was dramatically elevated in the serum of breast cancer patients compared to that of healthy donors, indicating that IL20RA signaling may play an important role in the progression of cancer." (PMID 33456560, 2021). "IL-19 expression levels have proven to predict worse disease-specific survival and metastasis-free survival, and it is believed that IL-19 acts primarily as a local mediator in the microenvironment that affects breast cancer cells and that acts in an autocrine manner in breast cancer." (PMID 30648081, 2018). "In this way, targeting IL19 could become a good therapy for breast cancer patients." (PMID 26979459, 2016). "Thus, IL-19 expression in tumor cells is hypothesized to be involved in tumor progression and to correlate with the clinical outcome of breast cancer." (PMID 23710200, 2013). "Antagonizing IL-19 might have therapeutic potential in breast cancer." (PMID 23710200, 2013). "In this study, we have highlighted the significance of TGFβ-1, IL19, CXCR4, BMP1, IL1A, VCAN, PDK1, and WNT2 in breast cancer pathology." (PMID 41348904, 2025). "By employing UALCAN, we examined the pattern of expression for TGFβ-1, IL19, CXCR4, BMP1, VCAN, and WNT2 in breast cancer." (PMID 41348904, 2025). "We compared the TGFβ-1, CXCR4, IL19, BMP1, VCAN, and WNT2 expression in different subtypes of breast cancer, and the results demonstrated that BMP1, and WNT2 were consistently overexpressed in HER-2 subtype." (PMID 41348904, 2025). "Secondly, a direct correlation was found between the concentration of IL-19 and TNF-α and tumour grade in breast cancer patients." (PMID 35928364, 2022). "Amplification of IL19, IL20, and IL24 co-occurs in ~9% of breast cancer patients, while the rate of IL26 amplification is only 2.4%." (PMID 33456560, 2021). "The most frequent gains found in our BRCAX tumors have been previously observed to be amplified in breast cancer, and contain at least four genes of interest PDE4DIP/Myomegalin, IL19, IL20 and FAIM3." (PMID 26979459, 2016). "Cytokines produced by cancer tissue and the expression of interleukin (IL)-1β, IL-6, IL-8, IL-10, IL-12, and IL-19, monocyte-chemoattractant-protein (MCP-) 1, and macrophage-inflammatory-protein- (MIP-) 1β are upregulated in breast cancer." (PMID 23710200, 2013). "Changes in the relative concentration of some cytokines, such as IL-1, IL-6, IL-11, and IL-19, and transforming-growth-factor- (TGF-) β, mediated both directly and indirectly by the tumor stimulate breast cancer proliferation and invasion." (PMID 23710200, 2013). "A functional hypoxic response element has been found on IL-19 promoter, and hypoxia induces IL-19 expression consistent with the increased expression of CXCR4 in breast cancer cell lines." (PMID 23710200, 2013). "Other studies indicated that some interleukins, especially IL-19, act as mediators in breast cancer, where high disease-specific survival (DSS) and metastasis-free survival (MFS) were noticed in patients with low levels of IL-19 compared with patients with high levels of IL-19." (PMID 35928364, 2022). "We previously generated the anti-human IL-19 mAb 1BB1, which showed specific neutralization activity against human IL-19 in a mouse model of breast cancer, but 1BB1 did not effectively neutralize mouse IL-19 protein in vivo (data not shown)." (PMID 31114590, 2019). "Because stimulation with IL-6 induces IL-19 expression, there may be positive feedback between IL-6 and IL-19 that elicits the STAT3 signal and the progression of breast cancer." (PMID 23710200, 2013). "IL-19 induces IL-1β, IL-6, TGF-β, and MMP-2 in breast cancer cells." (PMID 23710200, 2013).
breast carcinoma (continued). "IL-19 acts in breast tumors in an autocrine manner and the expression and colocalization of IL-19 and its cognate receptors can be seen both in human (MCF-7 and Hs578T) and in mouse (67NR and 4T1) breast cancer cell lines." (PMID 23710200, 2013). "In addition, it is still unknown whether the effect of the IL-19/IL-20RB/STAT3 axis is specific to lung cancer or also applies to other cancer types, such as breast cancer." (PMID 36006737, 2022). "Thus, patients with PR negative breast cancer had significantly higher levels of IL-19 compared to patients with PR positive breast cancer (p < 0.01)." (PMID 34554372, 2021). "However, the serum levels of IL-19 are unchanged with the tumor stage, which suggests that IL-19 levels in the local microenvironment are dominant rather than the systemic effect in breast cancer." (PMID 23710200, 2013). "In vitro assays showed that the mechanism of IL-19 in 4T1 cells is activating the intracellular signals STAT3, JNK, ERK, AKT, and NF-κb, which may be involved in cell proliferation and survival, but phosphorylation occurred only on JNK, ERK, and AKT in Hs578T human breast cancer cells." (PMID 23710200, 2013).
inflammatory bowel disease (11 papers, 2013 to 2024). A spectrum of small and large bowel inflammatory diseases of unknown etiology. "We have previously shown, using IL-19 gene-deficient (KO) mice, that IL-19 plays a protective role in inflammatory bowel disease and dermatitis." (PMID 37509702, 2023). "Furthermore, levels of IL-19, IL-20, IL-24 and IL-26 are also elevated in serum of patients with inflammatory bowel disease, which is associated with the intergenic 6q23 variants tagged by rs6920220." (PMID 27799070, 2016). "The primary objective of this study was to investigate any changes in IL-19 and IL-24 expression between inflammatory bowel disease (IBD) patients and healthy controls, as well as before and after the initiation of biologics." (PMID 39007024, 2024). "In inflammatory bowel disease, IL-19 exerts anti-inflammatory effect to hamper hyperactivation of both innate and acquired immunity." (PMID 33776998, 2021). "On the other hand, IL-19 also exerts anti-inflammatory activities in inflammatory bowel disease and vascular inflammatory diseases." (PMID 25794104, 2015). "We have previously analyzed the role of IL-19 in inflammatory bowel disease and dermatitis." (PMID 34944021, 2021). "However, the effects of IL-19 on inflammatory bowel disease are therapeutic and significantly reduced innate-mediated colonic inflammation in murine model." (PMID 23710200, 2013). "Therefore, we wondered if IL-19, which is involved in inflammation in inflammatory bowel disease and dermatitis, might play some role in liver inflammation in NASH progression." (PMID 34944021, 2021). "The IL-20 cytokines IL-19, IL-20, IL-22, IL-24, and IL-26 are elevated in autoimmune/inflammatory diseases, such as in the skin of patients with psoriasis, in synovial fibroblasts, and macrophages of patients with rheumatoid arthritis and in patients with inflammatory bowel disease." (PMID 29967613, 2018). "Recently, increased expression of IL-19, IL-20 and IL-24 has been demonstrated in the colonic mucosa and also in peripheral blood mononuclear cells (PBMCs) of patients with inflammatory bowel diseases (IBD)." (PMID 31973719, 2020).
autoimmune disease (9 papers, 2011 to 2024). A disorder resulting from loss of function or tissue destruction of an organ or multiple organs, arising from humoral or cellular immune responses of the individual to their own tissue constituents. "IL-19, a crucial member of the IL-20 subfamily, is associated with several inflammatory diseases and autoimmune diseases, participating in the Th2 type immunological response." (PMID 31379870, 2019). "Because EAE is a Th1 and Th17 cell-mediated autoimmune disease, we next assessed whether IL-19 deficiency would increase CNS infiltration of Th1 and Th17 cells." (PMID 33776998, 2021). "IL-19, as a new inflammatory factor in the regulation of the immune system, is related to the progression of many diseases, including autoimmune diseases, inflammation diseases and cancer." (PMID 35281428, 2022). "In this regard, the importance of IL-19, IL-27, and IL-35 in infections such as TB and in autoimmune diseases is under investigation." (PMID 22666281, 2012). "Our study, together with previously published reports detailing the significance of IL-19 in infectious, allergic and autoimmune diseases suggests a potential clinical application." (PMID 22110701, 2011). "Notch2 plays a major role in IL-19-mediated maturation of lung dendritic cells, which may have potential implications for the involvement of antigen-presenting cells in autoimmune diseases." (PMID 35846128, 2022). "Therefore, enhancement of IL-19 signaling represents a promising therapeutic strategy against MS and other Th17-mediated autoimmune diseases." (PMID 33776998, 2021). "Although IL-19 and IL-24 have been studied extensively in other autoimmune diseases, their exact role in IBD is not entirely clear." (PMID 39007024, 2024).
colitis (8 papers, 2013 to 2024). Inflammation of the colon. "To confirm the cause-effect relation between IL-19 in colitis and anxiety, we overexpressed IL-19 in colitis through an AAV-mediating strategy by colonic perfusion of AAV-IL-19-GFP or AAV-GFP." (PMID 36936941, 2023). "This possibility is supported by the experiments of Azuma etal who showed that IL-19−/− mice have higher susceptibility to acute DSS-induced colitis than wild-type mice." (PMID 24718601, 2014). "Knockout mice for IL-2 and IL-10 spontaneously develop colitis, and it was recently documented that IL-19-deficient mice present increased susceptibility to acute DSS-induced colitis." (PMID 24718601, 2014). "In experimental dextran sulfate sodium-induced acute colitis, IL-19−/− mice were more susceptible to colitis than were wild-type controls." (PMID 23468852, 2013). "A DSS/CUS comorbid model of colitis and anxiety was established to demonstrate whether IL-19 was associated with these comorbidities." (PMID 36936941, 2023). "Thus, we designated an intracellular bacteria S. choleraesuis carrying a eukaryotic-expressing plasmid encoding IL-19 to evaluate the therapeutic effect on murine colitis." (PMID 37375032, 2023). "Therefore, we planned to exploit S. cholersesuis carrying a eukaryotic expression plasmid encoding the IL-19 gene as a new gene therapeutic strategy in a DSS-induced murine colitis model." (PMID 37375032, 2023). "However, on the contrary, previous results indicated that the IL-19−/− mice were highly susceptible to DSS-induced colitis, resulting in severe weight loss and death." (PMID 36936941, 2023). "Furthermore, IL-19-deficient animals develop attenuated DSS colitis that is induced by disruption of the epithelial barrier with DSS." (PMID 29967613, 2018). "In order to identify the exact effect of IL-19 in the comorbidities due to colitis and anxiety, we infected the intestinal tract with the IL-19 overexpression virus." (PMID 36936941, 2023). "IL-19-deficient mice suffered from exacerbated experimentally induced colitis with the increased production of several proinflammatory cytokines, indicating IL-19 to be an anti-inflammatory cytokine in intestinal inflammation in mice." (PMID 37375032, 2023). "We also found that IL-10 expression was induced in IL-19-treated colitis mice and prevented inflammatory infiltrates and proinflammatory cytokine expression in these mice." (PMID 37375032, 2023). "Although we prove that S.C./pLJD-CMV-mIL19 can express the IL-19 gene in the colon extracts of the colitis mice, more specific investigations to prove the in vivo colon epithelial expression of IL-19 in these mice will be required in the future." (PMID 37375032, 2023). "In conclusion, the present study demonstrates for the first time that IL-19 is a gene therapy agent in a murine model of colitis." (PMID 37375032, 2023). "At day 3, IL-10 and IL-19 expression levels were increased in S.C./pLJD-CMV-mIL19-treated DSS colitis mice compared to control mice, as determined by RT-PCR." (PMID 37375032, 2023). "Previous studies also reported conflicting observations of IL-19 effects (pro-inflammatory vs. anti-inflammatory) even in similar mouse models of colitis, suggesting that the effects of IL-19 depend strongly on the condition and distribution of inflammation." (PMID 33931083, 2021). "In colitis models, both accelerated and attenuated DSS colitis has been reported in two different IL-19 KO mouse strains." (PMID 29967613, 2018). "Homozygous Il19-tdTomato reporter mice, in which tdTomato replaces exon 3 of the Il19 gene tdTomato, showed attenuated DSS colitis associated with reduced IL-6 production in macrophages." (PMID 29967613, 2018). "In mice, IL-19 up-regulates TNFα and IL-6 expression and its deficiency increases susceptibility to DSS-induced colitis." (PMID 24718601, 2014). "Data from a few animal studies showed that IL-19 might control intestinal inflammation and induce mucosal healing in experimental colitis models." (PMID 39007024, 2024).
colitis (continued). "Through the induction of IL-10, S. cholersesuis carrying the IL-19 gene may have therapeutic potentials for treating murine colitis." (PMID 37375032, 2023). "Likewise, geneexpression of the protective cytokines IL-19 and IL-33 in the colon ofgp130757F/F LysMcre/STAT3flox mice during acuteDSS-induced colitis was similar to the gene expression levels in WT mice." (PMID 26848037, 2016). "Based on ourfindings we therefore hypothesized that the altered colitis susceptibility ofgp130757F/F mice may be due to STAT3 activation in myeloidcells, and determined the expression of IL-19 and IL-33 in peritonealmacrophages of WT and gp130757F/F mice with and without LPSstimulation." (PMID 26848037, 2016). "Our results showed an increased IL-19 expression in IBD and especially CD patients versus healthy controls, which agrees with previous outcomes from the experimental colitis models (p<0.05)." (PMID 39007024, 2024). "In this study, we showed that IL-19 was an IL-10 inducer and that IL-10 production was stimulated at the early stage of DSS-induced colitis." (PMID 37375032, 2023). "Therefore, it may suggest that IL-19 gene delivery can ameliorate murine colitis." (PMID 37375032, 2023). "We found that simple IL-19 overexpression can produce anxiety-related behaviors and accelerate the DSS/CUS-induced colitis and anxiety phenomenons." (PMID 36936941, 2023). "We found that the DSS/CUS-induced comorbid model of colitis and anxiety showed up-regulated expression of IL-19 in the colon, and overexpression of IL-19 in the colon produced anxiety-related behaviors, and enhanced the sensitivity to the DSS/CUS-induced anxiety and symptoms of colitis." (PMID 36936941, 2023). "IL-19 is an activator of IL-10 transcription, and therefore, there is a hypothesis that might ameliorate active colitis; however, there is no sufficient data to support this." (PMID 39007024, 2024).
rheumatoid arthritis (8 papers, 2015 to 2024). A chronic, systemic autoimmune disorder characterized by inflammation in the synovial membranes and articular surfaces. "In the bootstrap resampling, we selected several important rheumatoid arthritis genes such as MMP genes (MMP1, MMP3), CCL genes (CCL3, CCL4, and CCL26), and IL genes (IL6, IL8, IL19, and IL24)." (PMID 31371761, 2019). "We confirmed this by measuring baseline IL-19 levels in rheumatoid arthritis and ulcerative colitis patients and found that IL-19 in these patients was not elevated above the upper limit of normal (geometric means of 17 and 9 pg/mL, respectively, data not shown)." (PMID 30914699, 2019).